NOP2 (NOP2 nucleolar protein)
Description:
S-adenosyl-L-methionine-dependent methyltransferase that specifically methylates the C(5) position of cytosine 4447 in 28S rRNA. Required for efficient rRNA processing and 60S ribosomal subunit biogenesis. Regulates pre-rRNA processing through non-catalytic complex formation with box C/D snoRNAs and facilitates the recruitment of U3 and U8 snoRNAs to pre-90S ribosomal particles and their stable assembly into snoRNP complexes. May play a role in the regulation of the cell cycle and the increased nucleolar activity that is associated with the cell proliferation.
Synonyms: NOL1; NSUN1; NOP120; p120
Tractability: Small molecule: a structure with a bound ligand is known. PROTAC: UniProt records ubiquitination sites on it; ubiquitination databases record sites on it; its protein half-life has been measured.
Target class: Enzyme; Transferase
Gene: Protein-coding gene on chromosome 12 (6,556,863 to 6,568,691, reverse strand). Ensembl gene ENSG00000111641.
Subcellular location: Nucleus, nucleolus; Nucleus
Subcellular location (Human Protein Atlas): Nucleoli
Pathways (Reactome):
Gene expression (Transcription): TFAP2A acts as a transcriptional repressor during retinoic acid induced cell differentiation
Metabolism of RNA: rRNA modification in the nucleus and cytosol
Gene Ontology:
Molecular function: protein binding; RNA binding; rRNA (cytosine-C5-)-methyltransferase activity; methyltransferase activity; RNA methyltransferase activity; S-adenosylmethionine-dependent methyltransferase activity
Biological process: positive regulation of cell population proliferation; ribosomal large subunit assembly; ribosomal large subunit biogenesis; rRNA processing; maturation of LSU-rRNA; rRNA base methylation; RNA processing
Cellular component: nucleolus; nucleus; nucleoplasm
Genetic constraint (gnomAD): Loss-of-function variants: 8 observed, 69.5 expected, observed/expected ratio (o/e) 0.12, 90% interval 0.067 to 0.21. The upper end of that interval is the gene's LOEUF score, 0.21, which puts it in group 1 of 6, group 1 being the genes least tolerant of losing a copy. Missense variants: 954 observed, 1,047 expected, observed/expected ratio (o/e) 0.91, 90% interval 0.86 to 0.96. Synonymous variants: 387 observed, 397.51 expected, observed/expected ratio (o/e) 0.97, 90% interval 0.89 to 1.06.
Homologues: Orthologues: pig NOP2 (85% identical), dog NOP2 (83% identical), rabbit NOP2 (80% identical), guinea pig NOP2 (79% identical), mouse Nop2 (76% identical), rat Nop2 (75% identical), zebrafish nop2 (50% identical), Drosophila melanogaster CG8545 (43% identical), Caenorhabditis elegans nsun-1 (33% identical). Paralogues in human: NSUN5 (15% identical), NSUN6 (15% identical).
Diseases named in the same sentence as NOP2 in open-access papers:
NOP2 is named in the same sentence as 59 diseases in open-access papers, as found by Europe PMC text mining. Sharing a sentence is not in itself a finding about the gene and the disease. The quoted sentences say what the papers report.
hepatocellular carcinoma (19 papers, 2015 to 2026). A malignant tumor that arises from hepatocytes. "As a member of the m5C methyltransferase family, elevated NOP2 promotes cell progression in colon cancer 20 and hepatocellular carcinoma 21 and is associated with poor prognosis in most cancers." (PMID 39309431, 2024). "Analyses of The Cancer Genome Atlas Liver–Hepatocellular Carcinoma (TCGA-LIHC) database showed that NOP2 was highly expressed in HCC and was associated with stage and tumor grade." (PMID 37398932, 2023). "NOP2/Sun RNA methyltransferase 4 (NSUN4) is a prognostic indicator for hepatocellular carcinoma (HCC)." (PMID 39634439, 2024). "NOL1 was also reported to promote hepatocellular carcinoma cell proliferation by TGF-β1/hPVT1/NOP2 pathway." (PMID 36698387, 2022). "In agreement with previous research reporting NOP2 in hepatocellular carcinoma, we found that NOP2 was highly expressed in CRPC tissues compared with the normal ones." (PMID 32554858, 2020). "PVT1 promotes cell progression, growth, invasion, and acquisition of stem cell-like properties by stabilizing FOXM1 and NOP2 proteins in breast cancer and hepatocellular carcinoma, respectively." (PMID 30809433, 2019). "Upregulation of PVT1 in hepatocellular carcinoma activates cell proliferation through stabilizing NOP2." (PMID 26517688, 2015). "For instance, HULC, up-regulated by CREB, could contribute to the initiation and progression of liver cancer through interacting with miR-372; lncRNA PVT1 favors hepatocellular carcinoma cell proliferation and stem cell-like property by stabilizing NOP2." (PMID 30987669, 2019). "High NOP2 expression was associated with shorter overall survival (OS) in 11 cancer types and poorer disease-free survival (DFS) in 13 cancer types (P < 0.05), including renal cell carcinomas, hepatocellular carcinoma, lower-grade glioma, and lung adenocarcinoma." (PMID 42136761, 2026). "A recent study has revealed that NOP2 regulates c-Myc mRNA stability and translation in an m5C-modified manner to promote glycolysis and hepatocellular carcinoma (HCC) progression." (PMID 39013911, 2024). "NOP2 is upregulated by microRNA PVT1 to promote hepatocellular carcinoma (HCC) proliferation and prostate cancer metastasis." (PMID 35562754, 2022). "lncRNA-mPvt1, as an example, is bound to NOP2 protein and enhances its stability, which is beneficial to cell proliferation, cell cycling, and the acquisition of stem cell-like properties in hepatocellular carcinoma (HCC) cells." (PMID 34660788, 2021). "A recent study has found that PVT1 increases NOP2 levels by enhancing the stability of the NOP2 protein in hepatocellular carcinoma and that the function of PVT1 in cell proliferation is dependent on the presence of NOP2." (PMID 26545364, 2015). "NOP2 overexpression enhanced XPD expression by elevating the m5C methylation of XPD, which contributed to inhibiting the proliferation, migration, and invasion of hepatocellular carcinoma (HCC) cells." (PMID 41462962, 2025).
prostate carcinoma (16 papers, 2020 to 2025). A carcinoma that arises from epithelial cells of the prostate gland. "NOP2 exhibits aberrant expression in a variety of cancers, such as renal clear-cell carcinoma, breast cancer, prostate cancer, and lung cancer, which is associated with poor prognosis." (PMID 39013911, 2024). "NOP2 is upregulated in various cancers, including lung adenocarcinoma, breast cancer, and prostate cancer, and it is associated with tumor aggressiveness." (PMID 35309925, 2022). "Moreover, the LINC00963/miR-542-3p/NOP2 axis could act as an inducer of prostate cancer metastasis and have a diagnostic and therapeutic potential for these patients." (PMID 34334108, 2021). "The expression of NOP2 is increased in prostate cancer tissue, potentially promoting the epithelial-to-mesenchymal transition (EMT) and influencing prostate metastasis." (PMID 40809690, 2025). "LINC00963 facilitated NOP2 by sponging the cancer inhibitor miR-542-3p to promote prostate cancer metastasis, where NOP2 promoted prostate cancer invasion by activating the epithelial–mesenchymal transition (EMT) pathway." (PMID 41462962, 2025). "In prostate cancer, the expression of NOP2 is elevated, which promotes metastasis and invasion through the EMT pathway." (PMID 35562754, 2022). "The long chain noncoding RNA LINC00963 promotes the metastasis of prostate cancer through regulating the expression of NOP2 by miR-542-3p." (PMID 34712323, 2021). "NOP2 (also named NSUN1, p120) has been improved primarily for its protumorigenic roles in many cancers such as prostate cancer, gallbladder cancer, lung adenocarcinoma, and several other cancers, consistent with our study." (PMID 34394351, 2021). "The literature suggests that NOP2 is highly expressed in prostate cancer, gallbladder cancer, and lung adenocarcinoma, while upregulated YBX1 plays a significant protumourigenic role in breast, renal, and gastric cancer." (PMID 34394351, 2021). "The high expression of NSUN5 can promote the proliferation of colon cancer cells, and the high expression of NOP2 can promote the metastasis of prostate cancer and the proliferation of liver cancer cells." (PMID 34631874, 2021). "For instance, overexpression of LINC00963 in prostate cancer triggered the NOP2-induced EMT pathway by reducing miRNA-542-3p expression, thereby promoting tumor progression." (PMID 34907204, 2021). "Recently study found Linc00963 could function as a ceRNA to upregulate nucleolar protein homolog 2 (NOP2) expression and promote cancer metastasis by sponging microRNA (miR)-542-3p in prostate cancer." (PMID 33643926, 2021). "A recently study identified Linc00963 could function as a ceRNA to upregulate NOP2 expression and promote cancer metastasis by sponging miR-542-3p in prostate cancer." (PMID 33643926, 2021). "However, the specific mechanism by which NOP2 mediates m5C regulation in prostate cancer remains unclear." (PMID 40809690, 2025). "It has been reported that NOP2 can be regulated by the long noncoding RNA, LINC00963, to promote metastasis of prostate cancer cells." (PMID 39013911, 2024). "In prostate cancer, LINC00963 promotes the expression of NOP2 by sponging the tumor suppressor miR-542-3p and facilitates the metastasis of prostate cancer." (PMID 34498706, 2021).
leukemia (12 papers, 2018 to 2025). A malignant (clonal) hematologic disorder, involving hematopoietic stem cells and characterized by the presence of primitive or atypical myeloid or lymphoid cells in the bone marrow and the blood. "In 5-AZA-resistant leukemia cells (ARLC), the interaction of NOP2, BRD4, and RNA pol-II is associated with the formation of an active chromatin structure with resistance to 5-AZA but is highly sensitive to the inhibition of BRD4 and NOP2." (PMID 35562754, 2022). "NOP2/NSUN1 depletion has been shown to suppress proliferation, migration, and invasion of colon cancer cells and sensitize leukemia cells to 5-aza-cytidine treatment." (PMID 36161484, 2022). "Our study demonstrated that RNA cytosine methyltransferase NOP2/NSUN1 and NSUN2 interact with BRD4 and the elongating form of RNAP (CTD-S2P) to form a transcriptionally active chromatin structure in leukemia cells." (PMID 33922187, 2021).
breast carcinoma (7 papers, 2019 to 2023). "NSUN1 (aka NOL1, NOP2 and p120) is a well-known tumor proliferation associated nucleolar protein and its expression levels predict breast cancer disease progress and patient survival." (PMID 33922187, 2021). "Furthermore, the upregulation of NSUN2 and NOP2 mRNA was significantly associated with shorter disease-free survival in breast cancer patients." (PMID 35562754, 2022). "In breast cancer cells, the phytochemicals sulforaphane (SFN), ursolic acid (UA), and betulinic acid (BA) can reduce the expression of NOP2 and inhibit cell proliferation, possibly contributing to reduced translation efficiency caused by interference of ribosome formation." (PMID 35562754, 2022).
colon cancer (7 papers, 2021 to 2025). "Transcriptome analysis of nucleolar protein p120 (NOP2)-deficient vs. NOP2-expressing human colon cancer cells identified the MUC19 gene as significantly upregulated, and T1D as a gene pathway most significantly affected, by NOP2 silencing." (PMID 35479093, 2022). "Compared with the healthy control group, NOP2 expression was significantly upregulated in colon cancer tissues and cells, while the NOP2 knockdown group demonstrated significantly inhibited colon cancer cell proliferation, migration, and invasion." (PMID 41462962, 2025).
glioma (6 papers, 2020 to 2026). A benign or malignant brain and spinal cord tumor that arises from glial cells (astrocytes, oligodendrocytes, ependymal cells). "According to a recent study on gliomas, five genes related to m5C methyltransferase were identified to construct a risk signature (5MM) and were used to predict glioma prognosis, including NOP2, NSUN4, NSUN5, NSUN6 and NSUN7." (PMID 36637205, 2023). "We obtained six genes associated with prognosis (P < 0.01), among which NOP2, NSUN2, NSUN4, NSUN5, and NSUN7 acted as risk factors (HR > 1), and NSUN6 played a protective role (HR < 1) in gliomas." (PMID 32974125, 2020). "In glioma, methylation of ATX mRNA at the 3′-UTR by NOP2/Sun RNA methyltransferase 2 (NSun2) enhances ATX mRNA nuclear-to-cytoplasm transportation and upregulates its expression, a sequence of events that leads to enhanced migratory capacity in glioma cells." (PMID 38607068, 2024). "The results showed that NSUN4, NSUN7, DNMT1, DNMT3B, DNMT3A, NOP2 and NSUN5 were negatively correlated with the overall survival of low‐grade glioma, while NSUN6 was positively correlated with the overall survival." (PMID 33400376, 2021). "All five RNA:m5C methyltransferase genes, NOP2, NSUN4, NSUN5, NSUN6, and NSUN7, were differentially expressed between normal brain tissues, low grade and high grade glioma tissues." (PMID 32974125, 2020). "The expression of NOP2, NSUN2, NSUN4, NSUN5, and NSUN7 were positively correlated in gliomas." (PMID 32974125, 2020). "Furthermore, as shown in the figure, we found that the protein expression of NOP2 and NSUN4 in high-grade glioma tissues were much higher than those in low-grade glioma tissues." (PMID 32974125, 2020). "In this study, we comprehensively studied the expression profiles of the NOL1/NOP2/sun domain RNA methyltransferase family, which are RNA:m5C methyltransferases, using the RNA sequencing data from the CGGA (n = 306) and TCGA (n = 616) datasets and aimed to investigate its prognostic value in glioma." (PMID 32974125, 2020).
ovarian carcinoma (6 papers, 2022 to 2026). A malignant neoplasm originating from the surface ovarian epithelium. "In the pan-cancer data on genes coding for RNA m5C regulatory proteins, it was found that the mutations and amplifications of NOP2 in ovarian cancer were the second highest." (PMID 37800580, 2023). "Genetic alterations of NOP2 were most frequent in ovarian cancer (6.1%) and patients with NOP2 genetic alterations were associated with poorer OS, DSS, and PFS in the cBioPortal cohort analysis." (PMID 42136761, 2026). "Our analysis suggests that the expression of RAPGEF4 in the cAMP signaling pathway is obviously decreased in ovarian cancer cells with stable knockdown of NOP2 expression compared to control cells." (PMID 37800580, 2023). "We analyzed the expression of NOP2 protein in ovarian cancer cell lines through the Expression Atlas dataset P×D030304and found that the HGSOC cell lines Hey and Caov3 were ranked eighth and ninth, respectively." (PMID 37800580, 2023). "Notably, NOP2 facilitated the proliferation of ovarian cancer cells in vitro and in vivo in this study." (PMID 39013911, 2024). "Although NSUN2 is the main methyltransferase for m5C methylation on mRNA, we extended to explore the expression of all potential m5C methyltransferases (NOP2, NSUN3, 4, 5, 6, 7, and DNMT2) in cervical cancer, ovarian cancer, and endometrial cancer." (PMID 35280737, 2022).
lung adenocarcinoma (5 papers, 2021 to 2026). A carcinoma that arises from the lung and is characterized by the presence of malignant glandular epithelial cells. "Herein, we investigated the expression of NOP2 in lung adenocarcinoma (LUAD) tissues and cells, and found that it was significantly upregulated." (PMID 39013911, 2024).
gastric cancer (4 papers, 2021 to 2026). A primary or metastatic malignant neoplasm involving the stomach. "Silencing NOP2/Sun RNA methyltransferase family member 2 (NSUN2) effectively inhibits gastric cancer (GC) progression but is limited by RNase degradation, rapid renal clearance, and low uptake." (PMID 40444266, 2025).
liver cancer (3 papers, 2017 to 2021). An epithelial or non-epithelial malignant neoplasm that arises from the liver. "In the development of liver cancer, both in vivo and in vitro studies demonstrate that lncPVT1 can prompt the proliferation and stem cell-like features of liver cancer cells by stabilizing an RNA binding protein named nucleolar protein (NOP2)." (PMID 29061150, 2017).